MCAM (melanoma cell adhesion molecule)
Diseases named in the same sentence as MCAM in open-access papers (continued):
Sharing a sentence is not in itself a finding about the gene and the disease.
melanoma (continued). "MCAM expression was observed in most naevi and melanoma samples analysed; 80% (4/5) naevi samples, 66.7% (4/6) primary melanomas and 100% (5/5) of melanoma metastases." (PMID 20421967, 2010). "MCAM can mediate both homotypic adhesion between melanoma cells, promoting local tumour growth, and heterotypic adhesion between melanoma cells and endothelial cells of blood vessels, facilitating metastatic spread." (PMID 20421967, 2010). "CD146 or Mel-CAM, MCAM or MUC18, is a highly glycosylated transmembrane glycoprotein part of the immunoglobulin (Ig) superfamily, initially recognized in melanoma cells." (PMID 21566786, 2010). "Melanoma progression is associated with several molecular changes including CCN1/CYR61, MCAM/MUC18 and PAR-1." (PMID 20805990, 2010). "The DNA-RNA layered Sindbis vector was used to overexpress the murine melanoma cell adhesion molecule (MCAM/MUC18) for vaccination against B16F10 murine melanoma cells." (PMID 21994535, 2009). "MCAM or CD146, a cell–cell or cell–matrix adhesion molecule, was first described in melanomas where a high level of CD146 expression is associated with a poor prognosis." (PMID 19123925, 2009). "The potential disadvantage is that the co-expression of MCAM by the melanoma cells can interfere with computer assisted, digital quantification of tubule formation." (PMID 16573823, 2006). "In melanoma, miR-516b-5p negatively regulates MCAM expression." (PMID 41388158, 2025). "MCAM was originally cloned and sequenced from a human melanoma cell cDNA library." (PMID 41388158, 2025). "Furthermore, MCAM has been described to mediate adhesion between melanoma and endothelial cells in vitro." (PMID 39945026, 2025). "MCAM has previously been described as a marker of melanoma disease progression and metastasis." (PMID 39945026, 2025). "In the present study, we aimed to investigate whether S100A8/A9 participates in GC progression, similar to its role in melanoma and breast cancers, via MCAM." (PMID 40924339, 2025). "In addition to MCAM‐mediated interactions, also other signalling mechanisms have been described to mediate melanoma–endothelial crosstalk such as Dll4‐Notch3 signalling." (PMID 39945026, 2025). "Due to the high expression of MCAM on both melanoma and endothelial cells, we hypothesised that MCAM might also promote the interaction of melanoma and endothelial cells." (PMID 39945026, 2025). "MCAM on melanoma cells could interact with molecules such as Laminin‐411 that are highly expressed in vessel walls and have been described as ligands for MCAM." (PMID 39945026, 2025). "We therefore hypothesised that the upregulation of MCAM on melanoma cells might reflect an embryonal transcriptional program." (PMID 39945026, 2025). "Because the knockout of MCAM disrupted the migration of melanoma cells on endothelial cells, we hypothesised that MCAM knockout might also reduce metastatic dissemination of melanoma cells." (PMID 39945026, 2025). "In our current work, we combine immunohistopathologic analyses of 69 advanced human primary melanomas and 42 melanoma metastases, bioinformatic analyses of published transcriptome datasets, and experimental studies in a mouse melanoma model to address the function of MCAM in melanoma progression." (PMID 39945026, 2025). "However, significant gaps remain in elucidating the downstream signaling pathways of MCAM in different cancer types, particularly melanoma and breast cancer." (PMID 40924339, 2025). "Interestingly, this interaction was stronger in melanoma cells with high MCAM expression compared to melanoma cells with low MCAM expression, suggesting that MCAM promotes the interaction of melanoma cells to endothelial cells and pericytes." (PMID 39945026, 2025). "To experimentally confirm the hypothesis that MCAM promotes the interaction of melanoma and endothelial cells, we generated MCAM knockout mouse melanoma cells." (PMID 39945026, 2025).
melanoma (continued). "In our bioinformatic analyses, we find abundant expression of MCAM in developmental melanocyte precursors, suggesting that the expression of MCAM in melanoma cells might reflect the reacquisition of stem‐like phenotypes of their embryonal precursors." (PMID 39945026, 2025). "Notably, in a different study, comparative proteomic analyses of plasma-derived extracellular vesicles from melanoma patients and healthy donors identified MCAM as one of the markers elevated in patients with melanoma." (PMID 41388158, 2025). "In addition, a moderate positive correlation is observed between ENG and MCAM (Melanoma Cell Adhesion Molecule), as well as between CD14 and CD44." (PMID 39594703, 2024). "Suppression of the cellular expression of poly-N-acetyl-lactosamine, a disaccharide that is recognized by galectin-3 and occurs in various N-linked carbohydrate structures of cell membrane glycoproteins including MCAM, showed to substantially reduce melanoma metastasis in mice." (PMID 36291660, 2022). "These discoveries led us to speculate that galectin-3 may be the unidentified natural binding ligand of MCAM in MCAM activation and MCAM-mediated melanoma progression." (PMID 36291660, 2022). "For instance, fluorescein isothiocyanate (FITC) or AlexaFluor 488, measured in the same channel, were assigned to antibodies recognizing melanoma cell adhesion molecule (MCAM or CD146), sialic acid binding Ig-like lectin H (Siglec-H), and glucocorticoid-induced tumor necrosis factor receptor (GITR)." (PMID 35145525, 2022). "Such investigations may help to gain insight into the role of MCAM glycosylation in MCAM-mediated actions in melanoma progression." (PMID 36291660, 2022). "Thus, galectin-3 is a natural binding ligand of MCAM in melanoma, and their interaction activates MCAM and promotes MCAM-mediated melanoma progression." (PMID 36291660, 2022). "Although originally identified as a melanoma cell adhesion molecule, CD146 has been detected in various cell types, including vessel constituting cells (ECs, pericytes, and SMCs), cancer-associated fibroblasts, extravillous trophoblasts, mesenchymal stem cells and lymphocytes." (PMID 36001597, 2022). "CD146 has been identified as a melanoma cell adhesion molecule." (PMID 34064074, 2021). "Melanoma cells do not undergo normal EMT changes, however they utilize EMT and MET (mesenchymal-to-epithelial transition) states that are mediated by adhesion molecules such as Cadherin-11, Connexis, integrins, N-cadherin and MCAM (CD146) which all are indicators of progressed melanoma." (PMID 35127523, 2021). "The onset of expression of MCAM/MUC18 and especially the β3-integrin subunit of αvβ3-integrin predicts progression from radial to vertical growth phase which elicits the metastatic potential in melanoma." (PMID 33870460, 2021). "The melanoma cell adhesion molecule (MCAM/MUC18), also known as CD146, is a member of the immunoglobulin superfamily, and a cell adhesion molecule that mediates adhesion between melanoma cells themselves, as well as adhesion between melanoma cells and endothelial cells." (PMID 34207884, 2021). "An in vivo study showed that an anti-MCAM/MUC18 antibody inhibited melanoma growth and metastasis." (PMID 34207884, 2021). "In addition, the ectopic expression of Cadherin 1 was associated with the downregulation of adhesion receptors, such as MCAM/MUC18 and β3 integrin subunit, resulting in suppression of melanoma cells invasion." (PMID 33980826, 2021). "Furthermore, the in vitro targeting MCAM using antibodies altered the biological properties of endothelial, melanoma, breast, ovarian, adenoid cystic carcinoma, and osteosarcoma cells, such as the proliferation or survival, migration, and invasion." (PMID 32204304, 2020). "In addition, a significant reduction after GET of pMCAM in MCAM expression in melanoma and carcinoma was confirmed at the mRNA level." (PMID 32204304, 2020).
melanoma (continued). "Furthermore, we wanted to compare the combined treatment in B16F10 melanoma, which is a more immunogenic tumor, with a high expression of MCAM to TS/A carcinoma, which is a less immunogenic tumor with a low expression of MCAM." (PMID 32204304, 2020). "After capture using ferrofluid coupled with antibodies against melanoma cell adhesion molecule (MCAM), circulating melanoma cells are identified by staining with antibodies against high molecular weight melanoma-associated antigen (HMW-MAA), also known as CSPG4." (PMID 32984308, 2020). "In addition, MITF-positive cells expressed the melanoma cell adhesion molecule (MCAM/CD146), which was initially identified as a marker of melanoma progression and metastasis, and MCAM expression was regulated by MITF." (PMID 33371469, 2020). "The expression of MCAM was significantly 25 times higher in B16F10 melanoma cells compared to TS/A carcinoma cells (Ct value for MCAM expression in B16F10 was 24.7 and for TS/A, it was 30.9; Ct value for GAPDH expression in B16F10 was 19.2 and for TS/A, it was 20.7)." (PMID 32204304, 2020). "A review showed that MCAM plays an important role in migration and invasion in melanoma cells." (PMID 33371469, 2020). "Further oncosuppressive functions of LRF/ZBTB7A include S cell cycle arrest, promotion of apoptosis and repression of migration in gastric cancer, and suppression of metastasis through transcriptional repression of melanoma cell adhesion molecule (MCAM) in melanoma." (PMID 31823818, 2019). "CD146 (also known as MCAM) is a cell adhesion molecule that closely related with melanoma." (PMID 31281389, 2019). "Importantly, in our hands the anti-MCAM antibody clone (F4-35H7) used in the CellSearch studies was similarly effective in binding melanoma cells (FACS, immunostaining and spiked cell isolation) as the more readily commercially available clone P1H12." (PMID 30735560, 2019). "For patients with malignant melanoma, the presence in blood of mRNA encoding for tyrosinase, MAGE-3 (melanoma-associated antigen 3), MCAM (melanoma cell adhesion molecule), p97 (transitional endoplasmic reticulum ATPase) and HMBS (hydroxymethylbilane synthase) is typical." (PMID 31572192, 2019). "All these findings strongly support a reliable role of MCAM/MUC18/CD146 in melanoma progression." (PMID 28280601, 2017). "Interestingly, some other factors, as the MGAT5, MCAM and TGFβ1, cooperating in the induction of prometastatic phenotypes in melanoma, were induced by miR-222." (PMID 26912358, 2016). "This in turn leads to the recruitment of actin, myosin IIB, Fzd3, and melanoma cell adhesion molecule (MCAM) into an intracellular structure of melanoma cells asymmetrically at the cell periphery, where it triggers membrane contractility and nuclear movement in the direction of membrane retraction." (PMID 27571105, 2016). "Out of these, we isolated three antibodies, B6-11, B6-112 and B6-117, that exclusively target blood vasculature, and by using IP and LC-MS, one antibody specificity was identified as MCAM/CD146 revealing an antigenic link between blood endothelial and melanoma cells." (PMID 25993332, 2015). "This hypothesis is also in contrast with previously published data which clearly showed a role for MCAM in cell motility in melanoma." (PMID 25692137, 2015). "On the other hand, in contrast with several evidences supporting a role for MCAM overexpression in metastatic transformation of various types of tumors including melanoma prostate cancer and non-small-cell lung carcinoma, our data would suggest that a reduced expression of MCAM promotes migration." (PMID 25692137, 2015). "Furthermore, an MCAM antibody decreases melanoma cell invasion, tumor vascularization, matrix metalloproteinase-2 (MMP-2) expression and reduces formation of lung metastasis in nude mice." (PMID 26703751, 2015). "All these findings strongly support a reliable role of MCAM/MUC18 in melanoma progression." (PMID 24902661, 2014).
melanoma (continued). "Since our data on the sequential MCAM/MUC18 expression were obtained from a relatively small cohort of melanoma patients, we cautiously chose the term “disease biomarker” to discuss its possible role in melanoma progression." (PMID 24902661, 2014). "MCAM, MMP-2, and Gal-3 expression in primary melanoma have been linked to poorer overall survival and could be used in combination with current prognostic indicators to identify patients at high-risk of recurrence." (PMID 24069584, 2013). "Endothelia and melanoma express high levels of MCAM, and as melanoma cell interactions with vascular endothelia are a key part of the metastatic process, it is likely MCAM on both of these cells contributes to melanoma metastasis." (PMID 24069584, 2013). "In conclusion, MCAM expression in a primary melanoma appears to increase the likelihood of metastatic spread and may assist to stratify patients into low and high-risk of recurrence at diagnosis." (PMID 24069584, 2013). "The uropod-like structure for melanoma cells has also been correlated to invasion in vitro and lung colonization in vivo, which is notable since MCAM functions as a cell-cell adhesion molecule for endothelial cells and has been implicated in homing and extravasation." (PMID 24349113, 2013). "Follow-up studies found that MCAM is abnormally expressed in a variety of tumour tissues, including melanoma, prostate cancer, breast cancer and non-small cell lung cancer and that this abnormal expression is closely associated with tumour progression and metastasis." (PMID 22610942, 2012). "However, from a drug development perspective if metastases of metastases are a possibility, adhesion molecules like MCAM on melanoma, for example, remain a viable drug target even after the first metastases have been diagnosed." (PMID 22272201, 2012). "MCAM is involved in the pathogenesis of melanoma, breast carcinoma, and other cancers." (PMID 23251904, 2012). "Additionally, some of the genes regulated by AP-2α in melanoma, such as MCAM/MUC18 and MMP-2, are also regulated by the CREB transcription factor." (PMID 20805990, 2010). "PAX3 was also co-expressed with melanoma cell migration marker MCAM in dermal naevi and melanoma cell nests, but this downstream target of PAX3 was not present in normal epidermal melanocytes, suggesting differential roles for PAX3 in normal epidermal melanocytes and melanoma cells." (PMID 20421967, 2010). "Indeed, we have also shown that AP-2α regulates MCAM/MUC18 expression through direct binding to its promoter, suppressing tumorigenicity and metastatic potential of human melanoma cells." (PMID 20805990, 2010). "However, we found that BRG1 activated expression of other MMPs and integrins as well as MCAM, all of which have been shown to be important for promoting melanoma invasive ability and tumor progression." (PMID 20969766, 2010). "We also show that PAX3- positive epidermal melanocytes of normal skin are molecularly distinct from those of the hair follicle, which like melanoma cells express Melanoma cell adhesion molecule (MCAM, also known as MUC18/CD146), associated with cell migration and melanoma progression and metastasis." (PMID 20421967, 2010). "Indeed, the role of MCAM in melanoma spread is well established, and we have already shown its potential clinical application for the capture and enrichment of a circulating melanoma cell (CMC) subpopulation characterized by an impressive invasive capacity." (PMID 40332096, 2025). "In addition, functionalized nanoparticles tagged with ligands, antibodies, or peptides selectively recognize melanoma-specific markers such as glycoprotein 100 (gp100) and melanoma cell adhesion molecule (MCAM), thereby promoting drug accumulation in tumor tissue while minimizing systemic toxicity." (PMID 40142960, 2025).
melanoma (continued). "This study aimed to determine whether the circ_0079593, sponging miR-516b-5p, could modify the regulation of two melanoma-associated genes, Melanoma Cell Adhesion Molecule (MCAM) and Chromatin Assembly Factor 1 Subunit B (CHAF1B) in two different types of melanoma metastasis cell lines." (PMID 39766913, 2024). "All these results suggested that the inhibition of MCAM may have an effect on endothelial cells and tumor cells in vivo and encouraged the researches to use the MCAM target in studies in vivo, not only in melanoma but also in osteosarcoma, pancreatic tumors, and prostate cancer bone metastases." (PMID 32204304, 2020). "An added benefit of our method is that it enriched for a variety of melanoma CTCs; while it targets those detected by the CellSearch Kit (MCSP and MCAM positive), it also targets CTCs expressing melanoma initiating cell markers (ABCB5 and CD271), which might be excluded by other methods." (PMID 24915896, 2014). "Therefore, MCAM represents a potential target for gene therapy of melanoma, whose expression could be hindered with posttranscriptional specific gene silencing with RNA interference technology." (PMID 25350580, 2014). "Interestingly, the last MCAM/MUC18 positive at t0, a metastatic patient from primary occult melanoma (UPN7), after surgery and a vaccine therapy, missed definitely the molecular expression remaining negative and is still disease-free after 8 years from first diagnosis." (PMID 24902661, 2014). "Another example is circ_0079593, which is involved in the development and aggressiveness of melanoma by regulating CHAF1B (Chromatin Assembly Factor 1 Subunit B) and MCAM (Melanoma Cell Adhesion Molecule) genes through the inhibition of miR-516b-5p." (PMID 40869968, 2025). "MCAM, which responds to S100A8/A9, promotes lung-specific metastasis in melanoma cells expressing this receptor." (PMID 40924339, 2025). "We previously identified two key receptors involved in melanoma organ-specific metastasis: extracellular matrix metalloproteinase inducer (EMMPRIN) and melanoma cell adhesion molecule (MCAM)." (PMID 40924339, 2025). "These additional markers were identified in only one article within our systematic review, reporting the downregulation of MCAM (CD146) in glioblastoma 24, CLDN11 (claudin 11) in colon cancer 82, and TJP2 in melanoma and breast cancer." (PMID 40083695, 2025). "Tumor cells from both modalities were highly similar, and key melanoma marker genes—including S100A1, MLANA, MCAM, and PRAME—were consistently highly expressed." (PMID 41446065, 2025). "It promotes the maintenance of MCAM protein at high levels and elevates the stability of MCAM by glycosylation, thus maintaining the responsiveness of MCAM to S100A8/A9 to increase melanoma cellular migration and invasion." (PMID 37701037, 2023). "Preclinical therapies for mouse melanoma used SV and VEE viruses to express the tyrosinase-related proteins (TRP), TRP-1 and TRP-2 and the adhesion proteins MCAM/MUC18." (PMID 37834397, 2023). "In another study on melanoma, SIN DNA replicon-based expression of the cell adhesion molecule (MCAM/MUC18) resulted in protection of immunized mice against challenges with B16F10 melanoma cells in both primary and metastatic mouse tumor models." (PMID 36986808, 2023). "Further, in melanoma, KLK7 overexpression inhibited cell adhesion by lowering integrin expression and inducing spheroid formation by increasing MCAM/CD146 expression." (PMID 36905477, 2023). "The melanoma cell adhesion molecule (MCAM, CD146, MUC18), a member of the immunoglobulin superfamily of cell adhesion molecules, is a marker of melanoma metastasis." (PMID 36291660, 2022). "MCAM-mediated activation of PI4K signalling was reported to help recruitment of actin-linking ezrin–radixin–moesin to cell protrusions and promote melanoma cell motility." (PMID 36291660, 2022).